USP17L7 (ubiquitin specific peptidase 17 like family member 7)
Tractability: No criterion of Open Targets' tractability assessment is met for any kind of drug.
Gene: Protein-coding gene on chromosome 8 (12,132,417 to 12,134,099, reverse strand). Ensembl gene ENSG00000226430.
Subcellular location: Nucleus; Endoplasmic reticulum
Gene Ontology:
Molecular function: cysteine-type deubiquitinase activity
Biological process: regulation of apoptotic process; protein deubiquitination
Cellular component: endoplasmic reticulum; nucleus
Genetic constraint (gnomAD): Loss-of-function variants: 42 observed, 23.31 expected, observed/expected ratio (o/e) 1.8, 90% interval 1.37 to 1.97. The synonymous counts are far from expectation, so gnomAD's model fits this gene poorly and the ratio says little. Missense variants: 724 observed, 410.71 expected, observed/expected ratio (o/e) 1.76, 90% interval 1.66 to 1.87. Synonymous variants: 265 observed, 154.79 expected, observed/expected ratio (o/e) 1.71, 90% interval 1.55 to 1.89.
Homologues: Paralogues in human: USP17L8 (92% identical), USP17L2 (92% identical), USP17L4 (92% identical), USP17L11 (92% identical), USP17L20 (92% identical), USP17L22 (92% identical), USP17L17 (92% identical), USP17L18 (92% identical), USP17L19 (91% identical), USP17L24 (91% identical), USP17L25 (91% identical), USP17L26 (91% identical), and 59 more.